EIF3A (eukaryotic translation initiation factor 3 subunit A)
Description:
RNA-binding component of the eukaryotic translation initiation factor 3 (eIF-3) complex, which is required for several steps in the initiation of protein synthesis. The eIF-3 complex associates with the 40S ribosome and facilitates the recruitment of eIF-1, eIF-1A, eIF-2:GTP:methionyl-tRNAi and eIF-5 to form the 43S pre-initiation complex (43S PIC). The eIF-3 complex stimulates mRNA recruitment to the 43S PIC and scanning of the mRNA for AUG recognition. The eIF-3 complex is also required for disassembly and recycling of post-termination ribosomal complexes and subsequently prevents premature joining of the 40S and 60S ribosomal subunits prior to initiation. The eIF-3 complex specifically targets and initiates translation of a subset of mRNAs involved in cell proliferation, including cell cycling, differentiation and apoptosis, and uses different modes of RNA stem-loop binding to exert either translational activation or repression. (Microbial infection) Essential for the initiation of translation on type-1 viral ribosomal entry sites (IRESs), like for HCV, PV, EV71 or BEV translation. (Microbial infection) In case of FCV infection, plays a role in the ribosomal termination-reinitiation event leading to the translation of VP2.
Synonyms: EIF3S10; KIAA0139; eIF3-theta; eIF3-p170; TIF32; EIF3; P167; p180; p185
Tractability: Small molecule: a structure with a bound ligand is known. PROTAC: ubiquitination databases record sites on it; its protein half-life has been measured.
Gene: Protein-coding gene on chromosome 10 (119,033,670 to 119,080,835, reverse strand). Ensembl gene ENSG00000107581.
Subcellular location: Cytoplasm
Subcellular location (Human Protein Atlas): Cytosol; Nucleoplasm
Pathways (Reactome):
Metabolism of proteins: Formation of a pool of free 40S subunits; Formation of the ternary complex, and subsequently, the 43S complex; GTP hydrolysis and joining of the 60S ribosomal subunit; L13a-mediated translational silencing of Ceruloplasmin expression; Ribosomal scanning and start codon recognition; Translation initiation complex formation
Gene Ontology:
Molecular function: protein binding; RNA binding; translation initiation factor activity; structural molecule activity; receptor tyrosine kinase binding
Biological process: formation of cytoplasmic translation initiation complex; IRES-dependent viral translational initiation; viral translational termination-reinitiation; translation reinitiation; translational initiation; cytoplasmic translational initiation; negative regulation of ERK1 and ERK2 cascade
Cellular component: cytosol; eukaryotic translation initiation factor 3 complex; membrane; cytoplasm; eukaryotic translation initiation factor 3 complex, eIF3e; eukaryotic translation initiation factor 3 complex, eIF3m; eukaryotic 43S preinitiation complex; eukaryotic 48S preinitiation complex; microtubule; postsynaptic density; protein-containing complex
Genetic constraint (gnomAD): Loss-of-function variants: 18 observed, 147.93 expected, observed/expected ratio (o/e) 0.12, 90% interval 0.083 to 0.18. The upper end of that interval is the gene's LOEUF score, 0.18, which puts it in group 1 of 6, group 1 being the genes least tolerant of losing a copy. Missense variants: 1,154 observed, 1,602.3 expected, observed/expected ratio (o/e) 0.72, 90% interval 0.69 to 0.76. Synonymous variants: 487 observed, 533.26 expected, observed/expected ratio (o/e) 0.91, 90% interval 0.85 to 0.98.
Homologues: Orthologues: rabbit EIF3A (94% identical), pig EIF3A (94% identical), dog EIF3A (93% identical), mouse Eif3a (93% identical), guinea pig EIF3A (93% identical), chimpanzee EIF3A (90% identical), macaque EIF3A (89% identical), rat Eif3a (89% identical), tropical clawed frog eif3a (74% identical), zebrafish eif3s10 (73% identical), Drosophila melanogaster eIF3a (38% identical), Caenorhabditis elegans egl-45 (29% identical).
Diseases named in the same sentence as EIF3A in open-access papers:
EIF3A is named in the same sentence as 111 diseases in open-access papers, as found by Europe PMC text mining. Sharing a sentence is not in itself a finding about the gene and the disease. The quoted sentences say what the papers report.
breast carcinoma (30 papers, 2005 to 2024). "In addition, rs10787899 and rs3824830 SNPs in eIF3A were associated with an increased risk of breast cancer (all P < 0.01)." (PMID 34044876, 2021). "Among them, the expression of RBM15, VIRMA, HNRNPA2B1, and YTHDF1/2/3 were significantly upregulated, but METTL3, METTL14, METTL16, WTAP, FTO, YTHDC1, and EIF3A had lower expression in breast cancer compared to normal samples." (PMID 34804948, 2021). "By comparing tumor and normal samples, we found that six proteins were differentially expressed in breast cancer significantly (P < 0.001), including EIF3A, HNRNPA2B1, HNRNPC, RBMX, YTHDF1, YTHDF2." (PMID 33585234, 2020). "eIF3a was firstly found to be over expressed in breast cancer compared with paired normal tissues, it was thus intensively investigated in breast cancers." (PMID 26213845, 2015). "RNA sequencing identified that eIF3a was involved in the growth and migration of breast cancer MCF-7 cells." (PMID 26213845, 2015). "On the one hand, based on in vitro experiments in lung and breast cancer cell lines, eIF3a was suggested to be involved in the development of cancer and to be affiliated to sustained malignancy." (PMID 22619676, 2012). "Similarly, breast cancer patients with high eIF3a expression were more sensitive to anthracycline drugs and displayed better prognosis." (PMID 38589831, 2024). "eIF3a knockdown was found to reverse the malignant phenotype of lung and breast cancer cells." (PMID 38589831, 2024). "YTHDF3 promotes the translation of m6A-modified mRNAs of breast cancer brain metastasis-associated genes (e.g., ST6GALNAC5, GJA1, and EGFR) by recruiting eIF3a and increasing the expression of the corresponding proteins, which ultimately affects the brain metastasis of breast cancer." (PMID 39440064, 2024). "It has been reported that eIF3A is significantly highly expressed in breast cancer." (PMID 34044876, 2021). "EIF3A, also described as an oestrogen-responsive gene, can target ER-mediated signals and facilitate the cell proliferation and/or migration of ERα-positive breast cancer cells." (PMID 34044876, 2021). "Additionally, the subunits eIF3 a, b, c, e, and f have been found as the oncogene overexpressed in several cancers, including nonsmall-cell lung cancer, breast cancer, cervical carcinoma, esophagus squamous-cell carcinoma, gastric carcinoma, and osteosarcoma." (PMID 32565801, 2020). "In breast cancer with brain metastases, YTHDF3 enhances the translation of EGFR and VEGFA mRNA by binding to eukaryotic translation initiation factor 3 subunit A (eIF3a)." (PMID 39098905, 2024). "Consistently, the strong positive correlation between eIF3a and PPP2R1B expression was observed in melanoma, lung cancer and breast cancer." (PMID 34512348, 2021). "We revealed that higher mRNA expression of EIF3A was accompanied by better RFS in breast cancer, which is not consistent with its function as a proto-oncogene as reported." (PMID 35040374, 2022). "In addition, the correlation between eIF3a and PPP2R1B was also observed in lung cancer and breast cancer tissue, suggesting that the mechanism is universal." (PMID 34512348, 2021).
lung cancer (24 papers, 2001 to 2025). A malignant neoplasm involving the lung. "For example, eIF3a mutation was found to be related to acquired chemotherapy resistance in lung cancer, and a low-frequency missense variant in SPOCD1 was associated with reduced risk of gastric cancer." (PMID 38589831, 2024). "To confirm that eIF3a is associated with cisplatin chemotherapy resistance in lung cancer, we tested eIF3a mRNA and protein expression in A549 (cisplatin sensitive cell line) and A549/DDP cells (cisplatin resistant cell line)." (PMID 28074905, 2017). "Our previous studies found that eIF3a is highly expressed in lung cancer and promotes the proliferation, migration, and invasion of lung cancer cells." (PMID 38275418, 2024). "Recently, we screened 31 eIF3a-derived circRNAs, in which two circeIF3as were identified to be correlated with cisplatin drug sensitivity in lung cancer." (PMID 38275418, 2024). "Previous studies have suggested the involvement of EIF3a in tumorigenesis and drug resistance of lung cancer." (PMID 33634138, 2021). "Recently, it is found that the expression of hsa_circ_0004350 and hsa_circ_0092857, both derived from EIF3a, varies prominently in cisplatin-resistant lung cancer cell line and the parental cell line." (PMID 33634138, 2021). "In this work, we screened 31 EIF3a‐derived circRNAs, in which two circEIF3as were identified to be correlated with cisplatin drug sensitivity in lung cancer." (PMID 31197975, 2019). "This is the first study that exploits circRNAs screening from EIF3a in lung cancer, our findings provide a novel perspective on the function of EIF3a and circEIF3as in lung cancer." (PMID 31197975, 2019). "Our study for the first time revealed the expression signatures of the circRNAs transcripts derived from EIF3a in lung cancer." (PMID 31197975, 2019). "The results suggest that EIF3a has a significant effect on the survival rate of patients with lung cancer, but has little effect on the prognosis of patients with ovarian cancer." (PMID 31197975, 2019). "In conclusion, we systematically analyzed the expression of EIF3a in various tissues and tumors, and also discussed the prognostic value of EIF3a in lung cancer patients and ovarian cancer patients." (PMID 31197975, 2019). "In the present study, we found that the over expression of miR-488 inhibited cell proliferation, migration and invasion in a lung cancer cell line by directly downregulating eIF3a expression." (PMID 28074905, 2017). "In summary, we are first time to revealed that miR-488 directly targets eIF3a and decreases the expression of eIF3a, which play as tumor suppressor to reduce cell proliferation, migration and invasion in a lung cancer cell line." (PMID 28074905, 2017). "EIF3a is known as a tumor promoting factor, which induced us to investigate the influence of miRNA-488 on the malignant phenotypes in lung cancer cells." (PMID 28074905, 2017). "Our previous studied indicated that eukaryotic translation initiation factor 3a (eIF3a) increases the sensitive of platinum-based chemotherapy in lung cancer." (PMID 28074905, 2017). "In the current study, both XPC and p27Kip1 was down regulated by eIF3a, which was in agreement with our previous finds in the lung cancer." (PMID 26213845, 2015). "Our previous works showed that eIF3a was associated with well differentiation and SCC, and improved response in lung cancer patients to CT by down-regulating NER proteins." (PMID 24789280, 2014). "Eukaryotic initiation factor 3a (eIF3a), the largest subunit of eIF3 complex, had been identified over-expressing in lung cancer, and tumors of cervix, stomach, esophagus, nasopharynx, colon, and oral cavity." (PMID 24789280, 2014). "In our previous studies, the genetic polymorphisms of WISP1, eukaryotic translation initiation factor 3 (eIF3a) and copper transport protein 1 (CTR1) were shown to be associated with platinum-based chemotherapy response or toxicity in lung cancer patients." (PMID 25405734, 2014).
lung cancer (continued). "EIF3a upregulation in lung cancer patients also correlated with their response to platinum-based chemotherapy and contributed to increased cisplatin (cis-dichlorodiammine platinum(II) (CDDP)) sensitivity." (PMID 24386425, 2013). "Preliminary, suggestive data is available, as it was recently shown the treatment of A549 lung cancer cells with docetaxel upregulates eIF3a expression in vitro." (PMID 22619676, 2012). "All of us conjecture that circRNA derived from eIF3a may also have important regulatory functions in lung cancer." (PMID 38275418, 2024). "EIF3A knockdown or ectopic overexpression, respectively, increases or decreases cellular resistance to cisplatin in a number of cancer cell lines, including nasopharyngeal and ovarian carcinoma and lung cancer cell lines, likely due to EIF3A’s role in the regulation of NER proteins." (PMID 37445831, 2023). "Previous studies, including our own study, supported the hypothesis that eIF3a knockdown reduces the cellular response to cisplatin by regulating the expression of DNA repair proteins in lung cancer, nasopharyngeal carcinoma, and ovarian cancer." (PMID 34512348, 2021). "Based on our previous results that eIF3a expression correlated with DDP resistant in lung cancer, we next tested whether eIF3a also affected DDP response in EOC cell lines." (PMID 26213845, 2015). "Furthermore, some eIF3a polymorphisms were potentially considered as tools for diagnosis and pretreatment evaluation of DDP-based chemotherapy in breast and lung cancer." (PMID 26213845, 2015). "Moreover, when human lung cancer A549 cells were treated with high concentration of docetaxel, the expression level of eIF3a mRNA tended to increase in a time-depend manner." (PMID 24386425, 2013). "To evaluate the expression profile of m6A readers in lung cancer, we analyzed known readers, including YTHDF1/2/3, YTHDC1/2, HNRNPA2B1, HNRNPC/G, eIF3A, FMR1 and IGF2BP1/2, in LUAD and lung squamous cell carcinoma (LUSC) via the GEPIA database." (PMID 33232910, 2021). "In our previous study, eIF3a up-regulation was identified to be correlated with better prognosis and response to DDP-based chemotherapy in lung cancer patients." (PMID 26213845, 2015). "In this study, we noted that eIF3a was expressed at a lower level in the A549/DDP cell line compared with parental A549 cells, and identified miR-488 as a tumor suppressor that inhibited cell proliferation, migration and invasion in the A549 lung cancer cell line." (PMID 28074905, 2017). "However, the results were not consistent: patients with a higher expression of eIF3a have a better prognosis in lung cancer, esophageal cancer, ovarian cancer, cervical cancer, and bladder cancer, whereas opposite results were observed in patients with liver cancer and pancreatic cancer." (PMID 37152897, 2023).
ovarian carcinoma (12 papers, 2015 to 2023). A malignant neoplasm originating from the surface ovarian epithelium. "Immunohistochemistry and western blot was used to determine the expression of eIF3a in 126 human ovarian cancer tissues followed by association analysis of eIF3a expression with patient's response and survival." (PMID 26213845, 2015). "eIF3a expression was associated with response of ovarian cancer patients to DDP-based chemotherapy and their survival." (PMID 26213845, 2015). "Furthermore, analysis of existing patient database shows that eIF3a expression associates with better overall survival of breast, gastric, lung, and ovarian cancer patients." (PMID 32974334, 2020). "EIF3A expression levels also correlate with better response to platinum-based chemotherapy in lung and ovarian cancer patients." (PMID 34645978, 2021). "As shown in our previous study, eIF3a increases the sensitivity of ovarian cancer and non-small cell lung cancer to platinum-based chemotherapy, and the patients with a high level of eIF3a have a better prognosis." (PMID 34512348, 2021). "Breast, gastric, lung, and ovarian cancer patients with a high eIF3a expression level all had better overall survival than patients with a low eIF3a level." (PMID 32974334, 2020). "In summary, we showed that eIF3a expression level correlates with responses of ovarian cancer patients to DDP-based chemotherapy and their survival." (PMID 26213845, 2015). "eIF3a improves ovarian cancer patients' response to DDP-based chemotherapy via down regulating XPC and p27Kip1." (PMID 26213845, 2015). "We found that eIF3a expression correlated with response of ovarian cancer patients to DDP-based chemotherapy." (PMID 26213845, 2015). "Indeed, we observed that patients with a high level of eIF3a expression have significantly better overall survival than patients with a low eIF3a level in breast, gastric, lung, and ovarian cancers." (PMID 32974334, 2020). "The role of these molecules in eIF3a regulating ovarian cancer platinum response still remains unclear." (PMID 26213845, 2015). "In this study, we explored the role of eIF3a in DDP response in ovarian cancer treatments." (PMID 26213845, 2015). "We also showed that eIF3a may regulate the response of ovarian cancer cells to DDP via down regulating XPC and p27Kip1." (PMID 26213845, 2015). "The current study aims to test the hypothesis that eIF3a may affect the drug response and prognosis of ovarian cancer patients receiving platinum-based chemotherapy by regulating xeroderma pigmentosum complementation group C (XPC) and p27Kip1." (PMID 26213845, 2015). "Thus, the correlation of eIF3a expression and ovarian cancer patients survival need to be validated in a larger sample size population." (PMID 26213845, 2015). "On the other hand, EIF3a was also reported to be up-regulated in urinary bladder cancer and acted with HER-2 in ovarian cancer." (PMID 27270324, 2016). "In the current study, we demonstrated that eIF3a also correlated with DDP-based chemotherapy responses and survival of ovarian cancer patients." (PMID 26213845, 2015).